SIRT3 (sirtuin 3)
Diseases named in the same sentence as SIRT3 in open-access papers (continued):
Sharing a sentence is not in itself a finding about the gene and the disease.
colorectal cancer (continued). "To study whether GA can affect the biological characteristics of colorectal cancer cells by inhibiting SIRT3 expression, we first overexpressed SIRT3 in colorectal cancer cells through lentivirus infection (AAV-SIRT3)." (PMID 34747319, 2022). "Finally, our in vitro results were confirmed in vivo, since GA significantly decreased the SIRT3 protein levels in colorectal cancer xenograft tissues along with their weights." (PMID 34747319, 2022). "Also, overexpression of SIRT3 reversed GA inhibitory effects on the proliferation of colorectal cancer cells in vivo." (PMID 34747319, 2022). "To test this hypothesis, we used flow cytometry to detect the cell cycle of WT and SIRT3-overexpressed (AAV-SIRT3) colorectal cancer cells after stimulation with 0 or 20 μmol/L GA for 24 h." (PMID 34747319, 2022). "Thus, we detected the effect of GA on the invasion and migration of colorectal cancer cells and their relationship with SIRT3 protein levels." (PMID 34747319, 2022). "In this regard, SIRT3 inhibitors may be an attractive drug for the therapy of colorectal cancer in combination with cisplatin." (PMID 35832551, 2022). "Interestingly, chemotherapeutic agent cisplatin inhibits expression of SIRT3 to induce acetylation of MTHFD2 in colorectal cancer cells." (PMID 32811824, 2020). "Moreover, our clinical analysis showed that high expression levels of SIRT3 in colorectal cancer patients were correlated with a shorter survival time, which is partially due to deacetylated SHMT2 and activated serine consumption in colorectal cancer cells." (PMID 30367038, 2018). "In colorectal carcinoma, SIRT3 was response to stress-induced apoptosis." (PMID 23272146, 2012). "Therefore, SIRT3 is a colorectal cancer oncogene, and GA might exhibit its potential anticancer activity in colorectal cancer by decreasing SIRT3 expression." (PMID 34747319, 2022). "Also, we located where SIRT3 was expressed in colorectal cancer cells using immunofluorescence." (PMID 34747319, 2022). "Also, overexpression of SIRT3 significantly attenuated this decrease in colorectal cancer cells number that could invade or migrate the transwell lower chamber." (PMID 34747319, 2022). "Here, we found that SIRT3 protein levels were significantly negatively associated with acetylated K88 MTHFD2 in our colorectal tumor tissues, which suggested that inhibitors of SIRT3 or MTHFD2 might be an attractive drug to combinate with cisplatin for colorectal cancer treatment." (PMID 32811824, 2020). "Thus, SHMT2 K95 acetylation, SHMT2 protein and SIRT3 may be potential biomarkers for colorectal cancer." (PMID 30367038, 2018). "We found that SIRT3 and SHMT2 were expressed simultaneously in colorectal cancer patients and that the acetylation of SHMT2 K95 was downregulated." (PMID 36684675, 2023). "It has been reported that SIRT3 can deacetylate MTHFD2 and promote its enzymatic activity in colorectal cancer cells." (PMID 35382861, 2022). "Finally, the six selected genes (SIRT3, PIK3CA, ITGA3, DAPK1, PAK1, and CASP3) have been reported in colorectal cancer." (PMID 38213716, 2024). "Interestingly, the chemotherapeutic agent 5-fluorouracil (5-Fu) inhibits the expression of SIRT3 and increases the acetylation levels of ALDH1L2 in colorectal cancer cells." (PMID 37507016, 2023). "SIRT3 can directly deacetylate the mitochondrial methylenetetrahydrofolate dehydrogenase/cyclohydrolase (MTHFD2) to promote cellular redox balance and drive colorectal cancer cell proliferation and diffusion." (PMID 35832551, 2022). "Available data suggest that Sirt3 is involved in cancer processes in CRC, as in most other cancers, but without further detailed research, we still do not know whether Sirt3 is a tumor promoter or tumor suppressor in colorectal cancer." (PMID 35440893, 2022).
colorectal cancer (continued). "Interestingly, SIRT3 inhibition by the chemotherapeutic agent cisplatin induced acetylation of MTHFD2 (the mitochondrial methylenetetrahydrofolate dehydrogenase/cyclohydrolase) at lysine 88 (K88) and disturbed cellular redox balance in colorectal cancer cells." (PMID 34360883, 2021). "SIRT3 overexpression in colorectal cancer cells also decreased FoxO3a acetylation and increased FoxO3a binding to the SOD2 promoter, whereas expression of a SIRT3 catalytic mutant did not affect the DNA binding ability of FoxO3a." (PMID 29099803, 2017).
Hyperglycemia (31 papers, 2018 to 2026). An increased concentration of glucose in the blood. "SIRT3 deficiency exacerbated hyperglycemia-induced mitochondrial damage and increased ROS accumulation." (PMID 40725501, 2025). "Sirt3 deficiency exacerbated hyperglycemia‐induced neuroinflammation and DNP by enhancing microglial aerobic glycolysis in vivo and in vitro." (PMID 39123294, 2024). "Retinal SIRT3 activation has been implicated in the protection of retinal capillary endothelial cells against hyperglycemia-induced damage in vitro and in vivo by endorsing redox defence via deacetylating manganese superoxide dismutase (MnSOD) and suppression of poly (ADP-ribose) polymerase." (PMID 34071497, 2021). "Moreover, these SIRT3/5−/− mice were susceptible to streptozotocin-induced hyperglycemia like controls, while showing only a modest inner retinal dysfunction." (PMID 31632409, 2019). "It is believed that hyperglycemia-related ROS and H2O2 play a significant role in the mesenchymal activation observed in states deficient in glucocorticoid receptor, SIRT3, or FGFR1." (PMID 40290438, 2025). "Blocking Akt activation by GSK69093 or metformin rescued the degradation of Sirt3 protein and transcription inhibition of Sirt3 mRNA, which substantially diminished hyperglycemia‐induced inflammation." (PMID 39123294, 2024). "Hyperglycemia induces metabolic reprogramming and inflammatory activation in microglia through the regulation of Sirt3 transcription and degradation." (PMID 39123294, 2024). "Metformin in vivo treatment alleviated neuroinflammation and diabetic neuropathic pain by rescuing hyperglycemia‐induced Sirt3 downregulation." (PMID 39123294, 2024). "Similar to SIRT1, SIRT3 has a defensive role against hyperglycemia by inactivating NF-κB-mediated pathways and downregulating the pro-apoptotic protein Bax." (PMID 35409409, 2022). "A study has shown that SIRT3 suppresses hyperglycemia-induced senescence of human diploid fibroblasts by deacetylating FOXO1." (PMID 34847835, 2022). "Hyperglycemia-induced oxidative stress led to a reduced expression of sirtuin 3 (SIRT3), thereby promoting forkhead box class O 3a (FOXO3a) acetylation in ventricular tissue and H9c2 cells." (PMID 36139819, 2022). "Hyperglycemia can suppress SIRT3 expression in the cerebral tissue, which augments neural oxidative stress, inflammation and apoptosis." (PMID 34071497, 2021). "None of these mice exhibited accelerated retinal dysfunction after induction of hyperglycemia, consistent with normal-appearing retinal morphology in hyperglycemic Sirt3−/− or Sirt5−/− mice." (PMID 30846716, 2019). "ICA was associated with reduced mtROS, cytosolic mtDNA, NLRP3 inflammasome activation, and pyroptosis in the hearts of DCM mice or hyperglycaemia-induced H9c2 cardiomyoblasts, which may occur in a SIRT3-dependent manner." (PMID 42292806, 2026). "Besides that, we also found that hyperglycemia induced Sirt3 degradation via the mitophagy‐lysosomal pathway." (PMID 39123294, 2024). "This suggests that hyperglycemia‐activated Akt signaling is critical for the decreased expression of Sirt3, which implies that dairy oral take metformin may sustain Sirt3 expression and inhibit DNP." (PMID 39123294, 2024). "Additionally, we observed that intraperitoneal administration of metformin rescued the hyperglycemia‐induced downregulation of Sirt3 at both mRNA and protein levels." (PMID 39123294, 2024).
Hyperglycemia (continued). "Reduced SIRT3 levels have been related to decreased viability in EC isolated from diabetic patients, further confirmed by in vitro low viability in SIRT3-silenced EC exposed to hyperglycemia." (PMID 37372041, 2023). "The overexpression of SIRT3 suppresses hyperglycemia-induced senescence of human diploid fibroblasts by deacetylating FOXO1 and increasing catalase and manganese superoxide dismutase (MnSOD) in WI-38 cell and is implicated as a potential target to treat diseases of senescence." (PMID 34847835, 2022). "The HFD-induced hyperglycemia in WT and Sirt3−/− mice was comparable." (PMID 35955472, 2022). "Hyperglycemia was shown to suppress SIRT3 in diabetic rats during intracerebral hemorrhages." (PMID 33806509, 2021). "Finally, SIRT1 and SIRT3 are involved in oxidative stress management: SIRT1 protects, through activation of FOXO1, cells against hyperglycemia-induced oxidative stress, whereas SIRT3 protects pancreatic cells in mice against palmitate-induced stress." (PMID 33806509, 2021). "We found that mice lacking Sirt3 (Sirt3−/−) or Sirt5 (Sirt5−/−) were equally susceptible to STZ-induced hyperglycemia compared to wild-type controls." (PMID 30846716, 2019). "Because past studies have demonstrated that chronic systemic hyperglycemia induces mitochondrial damage, we first evaluated whether there is increased SIRT3 or SIRT5 protein expression in retinas from STZ-induced hyperglycemic, wild-type mice." (PMID 30846716, 2019). "On the other hand, women with T2D showed significant change in SIRT3 level only, supporting the notion that the glycemic programming of gene expression in women with pGDM could result from a recent exposure to hyperglycemia induced by GDM." (PMID 29435415, 2018). "However, the role of Sirt3 in neuroinflammation induced by hyperglycemia remains unexplored." (PMID 39123294, 2024). "As expected, the protein expression of BCAT2 and PP2Cm were higher in NAF1L2-deficient or SIRT3-activated CF than those of control cells in response to HG stimuli, indicating that the NAF1L2/SIRT3 pathway was involved in hyperglycemia-induced dysfunction of BCAA catabolism." (PMID 37993768, 2023). "Data regarding the kidneys suggest that hyperglycemia may lead to an abnormal metabolism with high hexokinase and pyruvate kinase M2 activity, low Sirtuin-3 levels, an activated STAT3, and HIF1α signaling and an aberrant glycolysis similar to the Warburg effect in cancer cells." (PMID 34778040, 2021). "In STZ-induced diabetic mouse models knocked out for SIRT3 and SIRT5, hyperglycemia triggered neuroretinal dysfunction." (PMID 35409409, 2022). "Mice lacking both SIRT3 and SIRT5 (Sirt3−/−Sirt5−/−) were equally susceptible to STZ-induced hyperglycemia compared to control littermates of various genotypes, including Sirt3+/−Sirt5+/−, Sirt3−/−Sirt5+/−, and Sirt3+/−Sirt5−/− mice." (PMID 30846716, 2019). "As such, we induced hyperglycemia with streptozotocin in mice with monoallelic Nampt deletion from rod photoreceptors, mice lacking SIRT3, and mice lacking SIRT5 and tested multiple components of retinal function with electroretinography." (PMID 30846716, 2019). "Despite the abundant research on the anti‐inflammatory effects of Sirt3 by deacetylating mitochondrial or non‐mitochondrial proteins, such as IDH and SOD,28, 29 its specific role in central nervous system inflammation induced by hyperglycemia remains unclear." (PMID 39123294, 2024). "In Sirt3−/− DNP mice, metformin failed to alleviate the thermal hyperalgesia and tactile allodynia induced by hyperglycemia." (PMID 39123294, 2024). "On the other hand, mice lacking both SIRT3 and SIRT5 exhibited significantly more inner retinal dysfunction following induction of hyperglycemia compared to hyperglycemic littermate controls." (PMID 30846716, 2019).
Hyperglycemia (continued). "However, mice lacking both SIRT3 and SIRT5 (Sirt3−/−Sirt5−/− mice) exhibited significant evidence of inner retinal dysfunction after induction of hyperglycemia compared to hyperglycemic littermate controls, although this dysfunction was not accompanied by gross morphological changes in the retina." (PMID 30846716, 2019).
lung carcinoma (31 papers, 2017 to 2026). "Although SIRT3 mRNA expression varied across lung cancer cohorts, higher SIRT3 expression was associated with better overall survival in lung adenocarcinoma (LUAD), and protein-level analyses demonstrated reduced SIRT3 expression in lung cancer specimens." (PMID 42212315, 2026). "CSE induced low expressions of Sirt3 and SOD2 (P<0.01), and Sirt3/SOD2 was associated with poor prognosis in lung cancer patients (P<0.05)." (PMID 37183639, 2023). "Hypoxia-inducible factor (HIF-1α) is a therapeutic target in lung cancer, and the deacetylase sirtuin 3 (SIRT3) is closely associated with tumorigenesis." (PMID 37747648, 2023). "In the current study, we investigated underlying mechanism of SIRT3 in cisplatin resistance in lung cancer." (PMID 33655712, 2021). "By contrast to the tumor-suppressing role of SIRT2/4, the roles of SIRT1/6/7 and mitochondrial SIRT3/5 are strongly associated with drug resistance in lung cancer 119, 120, 124, 135, 142, 144, 146, 150-154." (PMID 31956359, 2020). "Furthermore, by using our in situ lung cancer implantation model, we found that Sirt3 deficiency causes increased sensitivity of cancer cells to radiotherapy." (PMID 34405009, 2021). "Immunohistochemical analysis of clinical specimens and western blotting of NSCLC cell lines further confirmed reduced SIRT3 expression in lung cancer." (PMID 42212315, 2026). "Recent studies have highlighted the significant role of SIRT3 in enhancing radiation resistance in lung cancer." (PMID 40710178, 2025). "Using both melanoma and lung carcinoma cells in culture, we delineated a previously undescribed mechanism of mtROS production by Arg-II, that is due to suppression of Sirt3 levels." (PMID 40177131, 2025). "Another important finding of our study is the role of Arg-II in nuclear deformation linking to enhanced migratory and invasion potential the melanoma and lung carcinoma cells, which is also mediated through the Sirt3-mtROS axis." (PMID 40177131, 2025). "MLT reverses the Warburg effect and inhibits lung cancer progression in lung cancer cells by stimulating Sirt3 to increase PDH production." (PMID 40756978, 2025). "First, in order to study the SIRT3 expression in lung cancer samples at the protein level, IHC assay of SIRT3 was analyzed using the Human Protein Atlas (HPA) database, and we selected 10 samples." (PMID 39501597, 2024). "SIRT3 promotes the doxorubicin (DOX)-resistance of lung cancer cells by enhancing autophagy to counteract DOX-induced senescence primarily through the inhibition of PI3K/AKT/mTOR signaling." (PMID 38773972, 2024). "Another compound melatonin, an endogenous chemical, increases SIRT3 expression in lung cancer cells and stimulates the pyruvate dehydrogenase complex (PDH) increasing ATP generation." (PMID 38773972, 2024). "In this study, we evaluated the effect of SIRT3 overexpression on A549 lung cancer cells under hypoxic conditions using in vitro experiments." (PMID 37747648, 2023). "In this study, we investigated the role of SIRT3 on tumor development in lung cancer cells and tumor-forming nude mice via the ROS-FPR1/HIF-1α axis in a hypoxic environment." (PMID 37747648, 2023). "Previous studies have demonstrated that SIRT3 overexpression enhances apoptosis of lung cancer cells and sensitivity to cisplatin." (PMID 37749074, 2023). "Honokiol blocks the growth of lung cancer cells by activating SIRT3 to inhibit HIF-1α expression, and also be used as adjuvant chemotherapy to prevent doxorubicin-induced cardiotoxicity in tumors transplanted mice." (PMID 35832551, 2022). "In lung cancer, Wang and colleagues showed that the activation of SIRT-3 by Adjudin inhibits cellular growth and metastasis by regulating the SIRT-3-mediated FOXO3a axis." (PMID 36080416, 2022).